TREX1 (three prime repair exonuclease 1)
Diseases named in the same sentence as TREX1 in open-access papers (continued):
Sharing a sentence is not in itself a finding about the gene and the disease.
cancer (continued). "Intriguingly, induction of Trex1 decreased dsDNA within exosomes derived from irradiated cancer cells, abolishing the activation of type I IFN production by DCs." (PMID 33238631, 2020). "When radiation is given in a single, high dose (>12 Gy), Trex1 is expressed at high levels and degrades the accumulated DNA in the cytosol of cancer cells, thus preventing type I IFN activation mediated by the cGAS pathway." (PMID 33142765, 2020). "By contrast, when radiation was given below the threshold dose for Trex1 induction, cancers cells can be optimally stimulated to produce IFNβ and activate specific DCs, which was essential for the priming of tumor-specific CD8+ T cells." (PMID 31695799, 2019). "For example, the radiation dose per fraction dictates the level of the exonuclease three prime repair exonuclease 1 (TREX1), which degrades interferon-stimulatory cytosolic dsDNA and thus abrogates the immunogenicity of irradiated cancer cells." (PMID 30577587, 2018). "Here, the authors show that Trex1 attenuates the immunogenicity of cancer cells treated with high radiation doses by degrading cytosolic DNA and preventing the activation of interferon response." (PMID 28598415, 2017). "We show that the DNA exonuclease Trex1 is induced by radiation doses above 12–18 Gy in different cancer cells, and attenuates their immunogenicity by degrading DNA that accumulates in the cytosol upon radiation." (PMID 28598415, 2017). "The other important genes in this pathway like Abl1, Gml, Brca1, Zak, Xrcc5, Trex1, Pms1, Ccnu and Apex2 were also up regulated in the cancer cells." (PMID 22321936, 2012). "Therefore, we interrogated the association between TREX1 copy number loss and overall survival (OS) or progression-free survival (PFS) in the TCGA Pan-Cancer Atlas studies." (PMID 40581636, 2025). "As a result, inhibition of TREX1 may be a potential target to stop cancer invasion and inhibit its further development." (PMID 39759116, 2025). "This suggests a possibility that some TREX1 copy number gain may have already existed in the germline of some patients with cancer." (PMID 40581636, 2025). "Intriguingly, Nader and colleagues have observed DNA damage after nuclear envelope rupture in the context of cancer, and they proved this to be TREX1-dependent even in the context of full-length TREX1, which can translocate to the nucleus under certain conditions." (PMID 41425849, 2025). "These discordant observations suggest there is additional nuance to be explored in this area; perhaps that there may be significant variation in the threshold dose for TREX1 activation in different cancers." (PMID 38659582, 2024). "Understanding the function of TREX1 as an immune checkpoint has implications for cancer therapy." (PMID 38881902, 2024). "Also, it has been reported that TREX1 expression is induced by high doses of radiation in different cancer cell lines to attenuate the immunogenicity derived from cytosolic DNA upon radiation." (PMID 39177280, 2024). "Of note, a recent study demonstrated that TREX1 is induced in mouse carcinomas by high radiation doses to suppress type I IFN response, whereas it was not induced by low radiation treatment, indicating that TREX1 plays a role as an upstream regulator of radiation-driven antitumor immunity." (PMID 39177280, 2024). "In recent years, interest in TREX1 has risen due to its potential as a cancer immunotherapy target, and TREX1 activity on ss- versus dsDNA, the purpose of its homodimer structure, and the source of TREX1’s DNA substrates in vivo remain areas of active interest." (PMID 37339225, 2023). "Although inhibition of TREX1 could be a useful strategy for cancer immunotherapy, profiling cellular functions in terms of its potential substrates is a key step." (PMID 37870446, 2023). "It is interesting to consider whether “anti-inflammatory” mechanisms like those exhibited by ADAR1 and TREX1 could explain some of the observations in cancer patients with elevated expression of IFITMs." (PMID 36435199, 2023).
cancer (continued). "Therefore, the fractionated dose above the threshold (varies between 12 and 18 Gy in different cancer cells) for inducing Trex1 can result in downstream abrogation of IFN-β production, reducing DC recruitment and activation." (PMID 36713375, 2022). "For instance, TREX1 is a druggable enzyme that could be inhibited to prevent the degradation of RS-induced cytosolic DNA and promote inflammation during cancer treatment." (PMID 34249949, 2021). "TREX1-mediated degradation of cytosolic DNA hinders the activation of the cGAS/STING pathway in the cancer cells themselves as well as in dendritic cells that uptake extracellular vesicles produced by the irradiated cancer cells." (PMID 33561212, 2021). "We tested the anti-cancer therapeutic potential of abolishing TREX1 exonuclease activity using the genetically precise TREX1D18N mice (D18N mice), that express the mouse TREX1 D18N allele from its endogenous promoter that controls the level of expression in the appropriate genomic context." (PMID 33868310, 2021). "A broader intriguing question is whether TREX1 would be a useful molecular target for treatment of other cancers." (PMID 32586373, 2020). "Together, these findings suggest that increased levels of Trex1 not only reduce cytosolic dsDNA within cancer cells to limit type I IFN production, but also Trex1 restricts the capacity for exosomes derived from irradiated cancer cells to activate type I IFN production in DCs." (PMID 33238631, 2020). "When radiation was delivered at a high dose, the induction of three prime repair exonuclease 1 (Trex1) in irradiated cancer cells can degrade the DNA accumulating in the cytosol, which precluded the activation of cGAS-STING-IFN-I pathway and dampens the radiation-induced immunostimulation." (PMID 31695799, 2019). "Thus, in all cancer cells tested high radiation doses induce the upregulation of Trex1, but the threshold dose at which it is sufficient to clear the cytosolic dsDNA varies in different cells between 12 and 18 Gy." (PMID 28598415, 2017). "Similar to the results obtained with the mouse carcinomas, marked upregulation of human Ifnb1 and Mx1 was seen after irradiation with 8 Gy X 1, which was further increased with 8 Gy X 3, while 20 Gy upregulated Trex1." (PMID 28598415, 2017). "It is tempting to speculate with respect to cancers that the IFITMs could potentially function in a broadly analogous manner to negative regulatory ISGs such as TREX1 and ADAR1, which negatively regulate antitumor immunity and thereby promote therapy resistance." (PMID 36435199, 2023). "As TREX1 acts as an upstream negative regulator of innate immunity, inhibiting its activity may enhance the response of innate immunity, and holds potential for use in cancer immunotherapy." (PMID 37870446, 2023). "Methylation and expression of TREX1 were associated with response to multiple drug categories, which may suggest a possible mechanism of vulnerability to Aurora kinase inhibitors for SCLC, which has low TREX1 expression compared to other cancer categories." (PMID 32586373, 2020). "We identified Trex1 as a key regulator of radiation-induced immunogenicity, and found that its expression is induced at levels sufficient to degrade cytosolic DNA by single doses of radiation with a threshold ranging from 12 to 18 Gy in different mouse and human carcinoma cells." (PMID 28598415, 2017). "TREX1 (Three prime repair exonuclease 1) acts as an innate immune checkpoint, particularly affecting the cGAS-STING pathway which is critical in the immune response against cancer." (PMID 38881902, 2024). "Targeting TREX1 in chemoresistant SCLC cells induces intrinsic innate immune activation, leading to compromised cancer cell viability." (PMID 39177280, 2024). "However, to the best of our knowledge, there is no studies associating TREX1 to hereditary cancer." (PMID 35181726, 2022).
cancer (continued). "We first screened the messenger RNA (mRNA) expression of the nucleotide degrading enzyme genes TREX1, SAMHD1, RNASEH2A, RNASEH2B, and RNASEH2C in 14 cancer types using TCGA RNAseq data." (PMID 29843367, 2018). "Indeed, our data demonstrate that targeting TREX1 not only enhances the sensitivity of chemoresistant SCLC to chemotherapy in vitro and in vivo but also activates the cGAS-STING pathway, producing an antiviral response in cancer cells." (PMID 39177280, 2024). "Although we cannot rule out involvement of TREX1 in cancer cells that do not show increased IFN expression after fractionated irradiation with 2 Gy (Colo320 and SW480), these cells still showed induction of ISG expression and a steady state in clonogenic survival." (PMID 33964942, 2021). "Additionally, the downregulation of TREX1 expression in senescent cells may contribute to the aberrant activation of the cGAS-STING pathway and the accumulation of cytoplasmic DNA observed in cancers." (PMID 38877472, 2024). "Interestingly, the downregulation of the cGAS/STING pathway itself was shown to be a predictive biomarker for certain cancer subtypes, opening up the potential to identify patient groups that could benefit from cGAS/STING re-enhancing immunotherapy agents such as ENPP1 or TREX1 inhibitors." (PMID 38022587, 2023). "In particular, TREX1 could have nuclear or mitotic functions that need to be further investigated to ensure that its inhibition would not further increase genomic instability in cancer patients." (PMID 34249949, 2021).
infection (13 papers, 2009 to 2025). The state of being infected such as from the introduction of a foreign agent such as serum, vaccine, antigenic substance or organism. "Physiological sources of inflammation including aging and infection might cause TREX1-mediated DNA damage that accumulates over many years." (PMID 38824133, 2024). "TREX1 polymorphisms may influence the course of infection and autoimmune manifestations." (PMID 31861565, 2019). "The present study investigated the association of the TREX1 531C>T polymorphism with the susceptibility to HTLV-1 infection, the development of infection-related symptoms, and the presence of ANAs." (PMID 31861565, 2019). "The possible role of TREX1 531C>T polymorphism has not yet been investigated in relation to the infection or progression of infectious diseases." (PMID 31861565, 2019). "However, the Trex1 gene was also significantly upregulated in all infection groups at 3 and 6 dpi." (PMID 40416961, 2025). "We also observed increased expression of the host DNase TREX1, which enables HIV to evade intracellular detection by degrading HIV DNA during infection." (PMID 37795301, 2023). "We further detected 28 of the ISG expression levels upon H37Rv infection at multiplicities of infection 2 (MOI = 2) for 6, 24, and 48 h and approximately 90% (25 out of 28) of the ISGs (except for LY6E, RTP4, and TREX1) were significantly increased in hMDMs." (PMID 30717477, 2019). "A well-described feature of HIV-1 replication in macrophages is the lack of induction of a robust type 1 IFN response upon infection, likely explained by the activity of the TREX1 exonuclease." (PMID 35328442, 2022). "Together, these data suggest that a weaker induction of SAMHD1, and possibly of TREX1, might facilitate HIV-1 replication and contribute to accumulation of HIV-1 RT products in cDCs from EC after ex vivo infection." (PMID 26067651, 2015). "Although TREX-1 promotes retroviral DNA degradation and influences the immune response and susceptibility to HIV infection, its exonuclease activity is not sufficient to control established infection." (PMID 37298611, 2023). "In this regard, the action of TREX-1 seems to contribute to camouflaging the presence of HIV-1 to the recognition of DNA sensors, inhibiting the intracellular recognition of the virus and the consequent antiviral responses against the infection, resulting in a higher viral load." (PMID 37298611, 2023). "Here we show that knocking down any of the components of the SET complex, an endoplasmic reticulum-associated complex that contains 3 DNases (the base excision repair endonuclease APE1, 5′-3′ exonuclease TREX1, and endonuclease NM23-H1), inhibits HIV-1 and HIV-2/SIV, but not MLV or ASV, infection." (PMID 19266025, 2009).
immune diseases (4 papers, 2017 to 2023). "In addition, Glab has a therapeutic effect on innate immune diseases caused by abnormal cytoplasmic DNA in Trex1-deficient mice." (PMID 38066431, 2023). "Further investigation is needed to better define this temporal regulation of OST and N-glycosylation during mitosis, which may shed light on the biology of the OST complex as well as mechanisms of immune diseases associated with TREX1 C terminus." (PMID 28297665, 2017). "Therefore, Compound C may have potential therapeutic values for being used as a potent inhibitor of dsDNA-induced autoimmune activation, such as treating immune diseases caused by Trex1 deletion." (PMID 32180716, 2020). "Thus, the cell-cycle-dependent post-translation modification of TREX1 regulates its interaction with OST, which may have important implications for immune disease associated with the DNase-independent function of TREX1." (PMID 28297665, 2017).
infectious disease (3 papers, 2019 to 2025). A disorder directly resulting from the presence and activity of a microbial, viral, or parasitic agent in humans. "The findings highlight the dynamic role of gigaxonin in enhancing antiviral innate immune responses by targeting both TREX1 and cGAS, suggesting that targeting gigaxonin may constitute a novel therapeutic approach for combating infectious diseases." (PMID 40936183, 2025). "Taken together, these findings show that the TREX1 rs3135941 (T/C) polymorphism located in the 5′ untranslated region (5′UTR) does not promote variations in TREX1 expression levels, regardless of ethnic differences or the presence or absence of autoimmune or infectious diseases." (PMID 38675842, 2024).
neurodegenerative disease (3 papers, 2018 to 2026). A disorder of the central nervous system characterized by gradual and progressive loss of neural tissue and neurologic function. "Relevant to the hallmarks of neurodegenerative disease, Cd38‐deficient astrocytes also had disruptions to genes that regulate DNA/RNA functions (Trex1), protein homeostasis (Ubb), and cellular bioenergetics (Cox10)." (PMID 41400119, 2026). "The other five genes, bound by Tau under HS conditions (as also Grm5), were chosen according to their implication in neurodegenerative diseases (Trex1, Dlg2, Dlg1, Xrcc6, Eif2a)." (PMID 30321409, 2018). "Furthermore, we provide evidence that a TREX1 mutation is the likely cause of HSP and reveal the ER Ca2+ homeostasis pathway, which has been shown to be impaired in many neurodegenerative diseases, is a candidate mechanistic pathway associated with HSP." (PMID 34997539, 2022). "In summary, the current study reveals TREX1 as a novel regulator of the BiP/GRP78 interaction and shows that TREX1 deficiency promotes ER stress-mediated neuronal cell death, which indicates that TREX1 may hold promise as a therapeutic target for neurodegenerative diseases such as HSP." (PMID 34997539, 2022).
vasculopathies (3 papers, 2020 to 2025).
heart disease (2 papers, 2024 to 2025). "Whilst our study is limited by the small samples size our signature is robust and agrees with recent literature examining the role of RIG-I and TREX1 in heart disease." (PMID 38746373, 2024).
inflammation (2 papers, 2020 to 2022). Aberrant reaction of the microcirculation characterized by movement of fluid and leukocytes from the blood into extravascular tissues. "Cell-type-specific inactivations of Trex1 in either NPCs or the microglia did not cause the mild brain inflammation of the full KO, but the microglia-specific inactivation of Trex1 caused a spontaneous interferon response in the CNS." (PMID 32630049, 2020).
neurologic disease (2 papers, 2018). "In some cases, such as the neurologic disease associated with TREX1 deficiency, it has been these differences that have highlighted the presence of an underlying pathogenic mechanism." (PMID 29922296, 2018).
connective tissue diseases (1 paper, 2025). "Our findings suggest that impaired DNA clearance by TREX1 contributes to inflammation mediated by interferon and supports its role in the pathogenesis of connective tissue diseases, such as SSc-ILD." (PMID 40843700, 2025).
inflammatory myopathy (1 paper, 2022). "In agreement, both TREX1 and RNASEH2B deficiencies have been clinically associated with inflammatory symptoms such as inflammatory myopathy and systemic inflammation." (PMID 35262626, 2022).
TREX1 also shares sentences with these, for which no sentence is quoted: chilblain lupus (5 papers); Encephalopathy (3); retinopathy (3); Cerebroretinal vasculopathy (2); colorectal cancer (2); Intellectual disability (2); Leukoencephalopathy (2); non-small cell lung carcinoma (2); prostate tumor (2); adenocarcinoma (1); adrenocortical carcinoma (1); Aicardi–Goutières Syndrome type 1 (1); Alzheimer disease (1); autism (1); autoimmune neurological disease (1); autoimmune vasculitis (1); autoinflammatory syndrome (1); B-Cell Lymphoma (1); Behçet disease (1); bladder cancer (1); bladder urothelial carcinoma (1); brain disease (1); brain tumour- (1); cataract (1); Cerebral Arteriopathy autosomal Dominant with Subcortical Infarcts and Leukoencephalopathy type 1 (1); cholangiocarcinoma (1); cleft lip (1); cognitive decline (1); cognitive disorder (1); complement deficiencies (1).
A further 64 diseases each share a sentence with TREX1 in 1 paper.